EGFR (epidermal growth factor receptor)
Diseases named in the same sentence as EGFR in open-access papers (continued):
Sharing a sentence is not in itself a finding about the gene and the disease.
lung adenocarcinoma (continued). "Among 92 patients with EGFR-mutant lung adenocarcinoma treated with EGFR-TKIs in the two cohorts, 88 cases experienced progression, and the median progression-free survival (PFS) was 12.1 months." (PMID 38902688, 2024). "In EGFR-mutated lung adenocarcinoma (LAD), CBL-c was observed to actively regulate the activation of EGFR through the processes of K6 and K11 biubiquitination, thus contributing to its carcinogenic function." (PMID 39130630, 2024). "Although targeted therapy against EGFR has demonstrated significant advancements in lung adenocarcinoma, while progress in lung squamous carcinoma has been relatively sluggish." (PMID 38769831, 2024). "EGFR is reported to be the most frequently altered driver gene of lung adenocarcinoma in Asian patients, with an incidence ranging from 40% to 50%." (PMID 39281386, 2024). "Further investigations are warranted to develop strategies that prevent or delay the emergence of these resistance mechanisms, ultimately improving outcomes for patients with EGFR-mutant lung adenocarcinoma." (PMID 39743996, 2024). "The interaction between the Hippo pathway and the EGFR signaling pathway in lung adenocarcinoma (LUAD) is intricate." (PMID 38499647, 2024). "Transcriptional upregulation of A3B and downregulation of UNG were subsequently validated in multiple oncogenic EGFR-driven cellular models of lung adenocarcinoma at both the RNA and protein levels." (PMID 38049664, 2024). "One disease that closely approximates the lineage transitions observed in prostate cancer is EGFR- or ALK-mutant lung adenocarcinoma, where NE transition is a mechanism of escape from EGFR or ALK inhibition." (PMID 39394434, 2024). "Univariate analysis showed that there were significant differences in N stage EGFR mutation status and LYM% between the two groups of patients with lung adenocarcinoma (P < 0.05)." (PMID 38605303, 2024). "Baseline characteristics of Stage IV lung adenocarcinomas underwent EGFR‐TKIs plus brain metastasis radiotherapy (N = 98) or bone metastasis radiotherapy (N = 85) between exon 19‐Del and 21‐L858R." (PMID 38659399, 2024). "EGFR signaling can promote the proliferation of lung adenocarcinoma by downregulating the E3 ligase NEDD4L." (PMID 39075515, 2024). "Wang S. compared EGFR mutations detected in MPE, plasma, and tissue in patients with lung adenocarcinoma." (PMID 39596989, 2024). "Herein, we report a case of BRAF V600E mutation in only one of the multiple intrapulmonary metastatic lesions during treatment with osimertinib for patients with lung adenocarcinoma with EGFR exon 19 deletion." (PMID 39139611, 2024). "A 58-year-old female patient (case NCCLu-045) with stage IV lung adenocarcinoma harboring EGFR L858R received two EGFR-TKIs (erlotinib and olmutinib) and multiple rounds of chemotherapy." (PMID 38398169, 2024). "A triple osimertinib/calcineurin A/trametinib combination of treatment overcomes acquired resistance to EGFR TKI in EGFR-mutant lung adenocarcinoma cells that overexpress PPP3CB." (PMID 39353739, 2024). "Evidence from a recent study suggests that HPV 16E6/18E6 oncoproteins and epidermal growth factor receptor (EGFR) expression serve as good prognostic factors in patients with lung adenocarcinoma." (PMID 39409943, 2024). "Highly prevalent mutations in genes such as EGFR, KRAS, and ALK contribute substantially to lung adenocarcinoma and are pivotal for recommending targeted therapies." (PMID 39323996, 2024).
lung adenocarcinoma (continued). "A study conducted on lung adenocarcinoma cells found that hsa_circ_0007312 promotes third-generation EGFR-TKI resistance through pyroptosis and apoptosis via the miR-764/MAPK1 axis." (PMID 38200584, 2024). "Radiomics combined with EGFR machine learning model is a new method to predict brain metastasis of lung adenocarcinoma." (PMID 38605303, 2024). "Several significant targetable pathways in lung adenocarcinoma have been discovered, including the Epidermal Growth Factor Receptor (EGFR), PI3K/AKT/mTOR, and RAS-MAPK pathways." (PMID 37768502, 2024). "Here, we present an unusual case of primary lung adenocarcinoma with colon metastasis harboring EGFR exon 19 deletion, initially presenting with GI bleeding." (PMID 38957515, 2024). "Adenocarcinomas with psammoma bodies are often associated with tyrosine kinase inhibitor-targetable driver mutations in EGFR (69.8%), ALK (13.2%), and ROS1 (1.9%), although the presence of psammoma bodies in ROS1-fused lung adenocarcinomas remains debated." (PMID 39391406, 2024). "The development of resistance to targeted therapies, as observed in this patient with the initial response to EGFR-TKIs followed by progression, is a significant challenge in the treatment of lung adenocarcinoma." (PMID 39193383, 2024). "In patients with lung adenocarcinoma with pleural metastases, the predictive value of pleural CEA for EGFR mutations indirectly reflects the value of pleural fluid as a genetic test specimen." (PMID 37775991, 2024). "The research advances our understanding of PD‐L1 expression's genomic context and immunotherapy response in EGFR/ALK wild‐type lung adenocarcinoma." (PMID 38396367, 2024). "The phenotypic transition from EGFR-mutant lung adenocarcinoma (LUAD) to small cell lung cancer (SCLC) is considered a clinical mechanism of resistance to EGFR inhibitors." (PMID 39802949, 2024). "For patients with stage IIIB-IV EGFRm lung adenocarcinoma treated with EGFR-TKIs, adding RT significantly improves overall survival." (PMID 39772073, 2024). "Advanced lung adenocarcinoma patients often develop resistance to EGFR tyrosine kinase inhibitors (EGFR-TKIs), leaving uncertainties regarding subsequent treatment strategies." (PMID 38402169, 2024). "The treatment of lung adenocarcinoma with the EGFR inhibitor erlotinib cannot avoid drug resistance and gradually leads to tumor progression." (PMID 38787372, 2024). "To provide background information, we included a comparison cohort consisting of patients with surgically resected wild-type EGFR lung adenocarcinoma." (PMID 39281386, 2024). "The CK5‐positivity rate was significantly higher in ALK‐positive lung adenocarcinomas compared with the wild‐type (WT) and was significantly lower in EGFR‐positive lung adenocarcinomas compared with the WT." (PMID 38400801, 2024). "Here we investigate TKI response in monolayer and spheroid culture using EGFR-driven lung adenocarcinoma and describe how the choice of culture method can influence the physiological relevancy of drug screen results." (PMID 38538642, 2024). "Biopsies were carried out, resulting in a diagnosis of poorly differentiated lung adenocarcinoma with a high expression of PDL-1 (60%) and L858R mutation in exon 21 of the EGFR gene (Oncomine Pan-Cancer Cell-Free Assay)." (PMID 40027142, 2024). "As in many other tumors, EGFR expression has been shown to be increased in lung adenocarcinomas, an early event in carcinogenesis." (PMID 38953007, 2024). "To establish the clinical relevance of increased PIM1/GSK3β signaling in mediating acquired resistance to osimertinib in NSCLC, we obtained CT images of three cases of advanced EGFR-mutant lung adenocarcinoma." (PMID 39227379, 2024). "We identified 52 patients of lung adenocarcinoma treated with an EGFR TKI plus an anti‐VEGF agent as their first‐line systemic treatment." (PMID 38523603, 2024).
lung adenocarcinoma (continued). "In the same way, Schoenfeld and collaborators, in a large cohort of lung adenocarcinoma, found that alterations in KRAS and MET were significantly associated with high expression of PD-L1, whereas EGFR mutations were associated with low PD-L1 levels." (PMID 38611088, 2024). "Another case involved a 38-year-old patient with EGFR exon 21 L8585R lung adenocarcinoma who developed SCLC transformation after receiving regular erlotinib treatment for 18 months." (PMID 38807858, 2024). "A significant advancement in the targeted treatment of lung adenocarcinoma has been identifying and developing epidermal growth factor receptor tyrosine kinase inhibitors (EGFR-TKIs)." (PMID 39772073, 2024). "A total of 237 patients with EGFR-mutant lung adenocarcinoma and BM met the inclusion criteria for this retrospective study, including 102 in the bevacizumab group and 135 in the non-bevacizumab group." (PMID 38478262, 2024). "The other patient (case NCCLu-157) was a 61-year-old man diagnosed with stage IV lung adenocarcinoma harboring EGFR exon 20 A763_Y764insFQEA." (PMID 38398169, 2024). "Acquired resistance to third-generation EGFR-TKIs represents a significant clinical challenge in the treatment of EGFR-mutant lung adenocarcinoma." (PMID 39743996, 2024). "For instance, EGFR-TKIs can enhance progression-free survival compared to conventional chemotherapy in lung adenocarcinoma patients, while most patients eventually developed resistance to EGFR-TKIs." (PMID 39311766, 2024). "We observed that PRSS1 and CTCF mutations in lung adenocarcinomas and skin melanomas show similar resistance-conferring effects to KRAS and NRAS mutations when treated with EGFR and BRAF inhibitors." (PMID 39160568, 2024). "A 63-year-old male patient with stage IV lung adenocarcinoma displaying EGFR 19 deletion (case NCCLu-263) received erlotinib as the first-line treatment." (PMID 38398169, 2024). "A total of 237 patients with EGFR-mutant lung adenocarcinoma and BM met the inclusion criteria for this retrospective study, including 102 patients in the bevacizumab treatment group and 135 in the non-bevacizumab group." (PMID 38478262, 2024). "The earliest and most frequent mutations in lung adenocarcinoma occurs in the KRAS gene and affects the EGFR/RAS/RAF signaling pathway." (PMID 38953007, 2024). "An increase in A3B and a decrease in UNG protein levels were detected in EGFR TKI-treated tumor tissues from three distinct oncogenic EGFR-driven CDX models of human lung adenocarcinoma." (PMID 38049664, 2024). "Osimertinib is effective against the T790M mutation and markedly improves survival outcomes for patients with advanced-stage EGFR-mutated NSCLC, especially for lung adenocarcinoma (LUAD), in whom previous regimens have failed." (PMID 39298415, 2024). "YAP also plays a crucial role in the resistance of lung adenocarcinoma to epidermal growth factor receptor tyrosine kinase inhibitors (EGFR-TKIs) by increasing the expression of AXL." (PMID 38339350, 2024). "Analysis of primary tumours from multifocal lung adenocarcinomas reported ~5% of EGFR/ALK co-alterations." (PMID 39695132, 2024). "MALAT1 rs3200401 genotype distribution and clinicopathologic characteristics of EGFR wild type lung adenocarcinoma patients." (PMID 38517388, 2024). "Generally speaking, the median PFS of advanced lung adenocarcinoma treated with an EGFR TKI is about 9–13 months as shown in several phase III randomized controlled trials." (PMID 38523603, 2024). "In this study, we observed 92 EGFR-mutant lung adenocarcinoma patients treated with EGFR-TKI, of which 88 cases experienced progression." (PMID 38902688, 2024).
lung adenocarcinoma (continued). "EGFR mutations drive tumorigenesis through the MAPK and PI3K signaling pathways for many cancers, including lung adenocarcinoma (LUAD), glioblastoma multiforme (GBM), colorectal adenocarcinoma (CRAD), and head and neck squamous cell carcinoma (HNSCC)." (PMID 38675381, 2024). "We considered colorectal cancer with microsatellite instability (MSI), lung adenocarcinoma that is PD-L1 positive, EGFR wildtype, and ALK wildtype, as well as lung squamous cell carcinoma that is PD-L1 positive." (PMID 38709075, 2024). "Pathologic sectioning of the lung lesion after puncture revealed invasive lung adenocarcinoma, and a genetic test revealed EGFR exon 21: L858R (64.60%)." (PMID 39029067, 2024). "For example, the model we present in this article focuses on EGFR-mutant lung adenocarcinoma and can be useful to create a synthetic control arm with a historical standard of care." (PMID 37667175, 2023). "EGFR-mutant (EGFRmu) lung adenocarcinoma (LUAD) has a distinct TME compared to EGFR wild-type (EGFRwt) LUAD." (PMID 38087217, 2023). "We introduced this construct into human EGFRdel19-dependent PC-9 lung adenocarcinoma cells and subsequently knocked out the endogenous EGFR gene." (PMID 37552050, 2023). "As well as EGFR mutation, KRAS mutation is also major targetable somatic variable in primary lung adenocarcinoma." (PMID 36918771, 2023). "Further studies with larger sample size are needed to confirm our findings and to explore the long-term survival of lung adenocarcinoma patients after EGFR-TKI targeted therapy." (PMID 37250563, 2023). "Ubiquitin-specific protease 22 (USP22) has been shown to prevent ubiquitination-mediated EGFR degradation and activate multiple EGFR downstream signaling pathways, thus conferring resistance to EGFR-TKIs in mutant lung adenocarcinoma cells." (PMID 36694209, 2023). "Our study revealed the possible role of E-cadherin and vimentin expression in EGFR-mutant lung adenocarcinoma." (PMID 37340370, 2023). "These therapies have shown some success, as in EGFR overexpressing head and neck, and lung adenocarcinoma." (PMID 37720348, 2023). "Activating oncogenic mutations in epidermal growth factor receptor (EGFR) are detected in up to 20% of lung adenocarcinomas (LuADCs) and are the most relevant predictor markers of response to EGFR-tyrosine kinase inhibitors (TKIs)." (PMID 38213544, 2023). "A positive correlation exists between EZH2 expression and EGFR expression in lung squamous cell carcinoma and lung adenocarcinoma, but it is weak (r = 0.1122, p = 0.0002)." (PMID 37069494, 2023). "We then analyzed the global metabolomic profiles of 72 cases with available EGFR status in the lung adenocarcinoma group." (PMID 37095081, 2023). "Further studies are recommended to clarify the role of these biomarkers in the pathogenesis of EGFR-mutant lung adenocarcinoma." (PMID 37340370, 2023). "Conversely, poor response to immunotherapy in epidermal growth factor receptor (EGFR)-mutant lung adenocarcinoma (LUAD) patients is closely related to the characteristics of immune microenvironment." (PMID 36756152, 2023). "In this paper, we presented an explainable radiogenomic workflow to characterize EGFR and KRAS mutations from the CT scans of lung adenocarcinoma patients." (PMID 37508774, 2023). "Resistance to epidermal growth factor tyrosine kinase inhibitors (EGFR-TKI) remains one of the major challenges in lung adenocarcinoma (LUAD) therapy." (PMID 37268635, 2023). "For the EGFR mutant lung adenocarcinoma with BM, the OS of EGFR 19del patients are is longer than of EGFR L858R mutant ones (31.17 vs. 21.90 mo, p = .013)." (PMID 35614541, 2023). "In this study, we have shown that pleural CD39 + CD8 + T cells are selectively elevated in lung adenocarcinoma (LUAD) with wild-type epidermal growth factor receptor (EGFRwt) compared to those with newly diagnosed mutant EGFR (EGFRmu)." (PMID 38087217, 2023).
lung adenocarcinoma (continued). "A recent study has shown that SIRT1 can selectively eliminate EGFR TKI-resistant cancer stem cells by regulating mitochondrial oxidative phosphorylation in lung adenocarcinoma." (PMID 37242510, 2023). "Epidermal growth factor receptor (EGFR)-mutant lung adenocarcinoma (LUAD) patients often respond to EGFR tyrosine kinase inhibitors (TKIs) initially but eventually develop resistance to TKIs." (PMID 37178919, 2023). "The delta radiomic model derived from follow-up non-enhanced CT images has the potential to provide a novel, reliable, real-time, and non-invasive detection of early acquired resistance to EGFR-TKI in patients with lung adenocarcinomas." (PMID 37730961, 2023). "This study aimed to construct an effective nomogram based on the clinical and laboratory characteristics to predict the prognosis of stage I lung adenocarcinoma with EGFR alteration." (PMID 37941434, 2023). "Taken together, the results of this study suggest that inhibition of CDK12/13 in combination with osimertinib has the potential to overcome osimertinib resistance in EGFR mutant lung adenocarcinoma patients." (PMID 37190191, 2023). "This study aimed to explore the efficacy and safety of combining epidermal growth factor receptor tyrosine kinase inhibitors (EGFR-TKIs) with ZiLongJin Tablet (ZLJT) in delaying acquired resistance in advanced EGFR-mutant lung adenocarcinoma (LUAD) patients." (PMID 37990309, 2023). "Compared to EGFR-TKIs alone, EGFR-TKIs combined with chemotherapy improved ORR and mPFS in cases of advanced lung adenocarcinoma with EGFR 19Del, L858R mutation." (PMID 37390279, 2023). "Other EGFR fusions have also been rarely reported in lung adenocarcinoma as well as colorectal adenocarcinoma." (PMID 37168365, 2023). "We have previously shown that SLURP-1 inhibits migration of lung adenocarcinoma A549 cells via interaction with α7-nAChR/EGFR/PDGFR complexes, while the anti-migration activity of Oncotag in A549 cells depends solely on interaction with α7-nAChR." (PMID 37854069, 2023). "The pathology confirmed lung adenocarcinoma with an epidermal growth factor receptor (EGFR) exon 20 insertion, a finding consistent with the initial lung surgery a decade ago." (PMID 38292996, 2023). "To the best of our knowledge, we are the first to describe a case of pretreated advanced lung adenocarcinoma with EGFR ex20ins benefiting from the combined furmonertinib and anlotinib for a long time." (PMID 36817153, 2023). "In contrast, inhibition of DCLK1 reversed the occurrence of EMT and reduced the resistance of lung adenocarcinoma cells to EGFR-TKI." (PMID 37239162, 2023). "In this real‐world study, we evaluate the efficacy and safety of adjuvant epidermal growth factor receptor tyrosine kinase inhibitors (EGFR‐TKIs) for resected stage IB lung adenocarcinoma." (PMID 37559419, 2023). "The effect of pulmonary TB on the epidermal growth factor receptor (EGFR) in patients with lung adenocarcinoma (LAC) was investigated in 2019, and a significantly higher mutation frequency was found than in patients without tuberculosis." (PMID 37342560, 2023). "They found that radiomics features extracted from CECT were better than that from NECT images in differentiating mutant and wild-type EGFR in advanced lung adenocarcinoma patients." (PMID 37914925, 2023). "ASK1-272a.a is a novel protein encoded by circASK1 that mediates the chemosensitivity-inducing effect of epidermal growth factor receptor (EGFR)-mutant lung adenocarcinoma." (PMID 37065861, 2023).